SLC48A1 (solute carrier family 48 member 1)
Description:
Heme transporter that regulates intracellular heme availability through the endosomal or lysosomal compartment. In macrophages of the reticuloendothelial system, is the heme transporter for heme-iron recycling. Essential for macrophage iron homeostasis, transports heme from the phagolysosome to the cytoplasm during erythrophagocytosis (EP).
Synonyms: HRG-1; hHRG-1; HRG1; FLJ20489
Tractability: Antibody: UniProt places it where antibodies can reach, with high confidence; its Gene Ontology location is reachable by antibodies, with high confidence; UniProt predicts a signal peptide or a membrane-spanning region.
Gene: Protein-coding gene on chromosome 12 (47,753,916 to 47,782,751, forward strand). Ensembl gene ENSG00000211584.
Subcellular location: Endosome membrane; Lysosome membrane; Cytoplasmic vesicle, phagosome membrane
Subcellular location (Human Protein Atlas): Vesicles
Gene Ontology:
Molecular function: heme binding; heme transmembrane transporter activity; protein binding
Biological process: heme transport
Cellular component: endosome membrane; lysosomal membrane; plasma membrane; lysosome; phagocytic vesicle membrane
Genetic constraint (gnomAD): Loss-of-function variants: 6 observed, 11.58 expected, observed/expected ratio (o/e) 0.52, 90% interval 0.28 to 1.02. The upper end of that interval is the gene's LOEUF score, 1.02, which puts it in group 4 of 6, group 1 being the genes least tolerant of losing a copy. Missense variants: 165 observed, 177.33 expected, observed/expected ratio (o/e) 0.93, 90% interval 0.82 to 1.06. Synonymous variants: 89 observed, 78.28 expected, observed/expected ratio (o/e) 1.14, 90% interval 0.96 to 1.36.
Homologues: Orthologues: macaque SLC48A1 (99% identical), dog SLC48A1 (95% identical), guinea pig SLC48A1 (95% identical), pig SLC48A1 (94% identical), mouse Slc48a1 (92% identical), rat Slc48a1 (90% identical), rabbit SLC48A1 (84% identical), chimpanzee SLC48A1 (75% identical), zebrafish slc48a1b (65% identical), tropical clawed frog slc48a1 (64% identical), zebrafish slc48a1a (62% identical), Caenorhabditis elegans hrg-1 (25% identical), and 3 more.
Diseases named in the same sentence as SLC48A1 in open-access papers:
SLC48A1 is named in the same sentence as 15 diseases in open-access papers, as found by Europe PMC text mining. Sharing a sentence is not in itself a finding about the gene and the disease. The quoted sentences say what the papers report.
hepatocellular carcinoma (2 papers, 2022 to 2025). A malignant tumor that arises from hepatocytes. "For example, a four-gene signature (ABCB6, FLVCR1, SLC48A1, and SLC7A11) was created to build diagnostic and prognostic models for hepatocellular carcinoma (HCC)." (PMID 40002678, 2025).
iron deficiency (2 papers, 2019 to 2026). "SLC48A1 deficiency results in impaired erythroid maturation and an inability to systemically respond to iron deficiency." (PMID 31571584, 2019). "Although Hmox1 was not upregulated, several heme-scavenging genes (Hpx, Lrp1/Cd91) were induced, while others involved in heme or biliverdin handling (Slc48a1/Hrg1, Pgrmc1, Blvrb) were downregulated, suggesting a compensatory shift in heme-related processes consistent with iron deficiency." (PMID 41598416, 2026).
anemia (1 paper, 2020). A reduction in the number of red blood cells, the amount of hemoglobin, and/or the volume of packed red blood cells. "We conclude that the sequestering of heme as hemozoin in the RES macrophage phagolysomes In SLC48A1 deficient mice is responsible for the progressive anemia." (PMID 34713217, 2020). "In SLC48A1-deficient mice on a 10 ppm iron diet we observed a progressive anemia that first becomes significant after 45 days on a low-iron diet." (PMID 34713217, 2020). "We predict that, particularly in areas of the world with iron-poor diets, idiopathic anemia may be caused by SLC48A1 variants." (PMID 34713217, 2020).
Bantu siderosis (1 paper, 2020). "In regions where dietary iron is not limiting, we predict that variants in the SLC48A1 gene could lead to iron loading in RES macrophages, as has been described for Bantu siderosis or African Iron Overload (AIO)." (PMID 34713217, 2020).
colon cancer (1 paper, 2021). "In this study, we revealed the prognostic value of iron metabolism-related genes SLC48A1 and SLC39A8 in colon cancer; however, their associated signaling pathways need to be further explored." (PMID 35118074, 2021). "Immunohistochemistry showed that the SLC39A8 level was downregulated in colon cancer tissues, and the SLC48A1 level was upregulated significantly in colon cancer tissues." (PMID 35118074, 2021). "In different datasets of patients with colon cancer, SLC48A1 and SLC39A8 gene markers showed good prognostic performance." (PMID 35118074, 2021). "SLC39A8 and SLC48A1 play a role in the development of colon cancer and might be potential therapeutic targets." (PMID 35118074, 2021). "Next, we analyzed the potential function of SLC39A8 and SLC48A1 in colon cancer." (PMID 35118074, 2021). "Furthermore, the mRNA levels of SLC39A8 and SLC48A1 were successfully knocked down using siRNA in colon cancer cells in vitro." (PMID 35118074, 2021). "Knocking down SLC39A8 promoted the proliferation of different colon cancer cell lines (DLD1, HCT116, and HT29), and silencing SLC48A1 suppressed the proliferation of colon cancer cells in vitro." (PMID 35118074, 2021).
endometriosis (1 paper, 2025). The growth of functional endometrial tissue in anatomic sites outside the uterine body. "In scatter plots, the positive slopes of the IVW algorithm indicated that BMP6 and SLC48A1 increased endometriosis risk." (PMID 41150779, 2025). "In forest plots, the overall effect sizes of SNPs for BMP6 and SLC48A1 were positioned to the right of zero, further suggesting their contribution to endometriosis susceptibility." (PMID 41150779, 2025). "RT-qPCR confirmed elevated expression of BMP6 and SLC48A1 in endometriosis samples relative to controls." (PMID 41150779, 2025). "Both BMP6 and SLC48A1 were consistently overexpressed in endometriosis, reinforcing their potential as biomarkers." (PMID 41150779, 2025). "The biomarkers BMP6 and SLC48A1 demonstrated significantly elevated expression in endometriosis samples, a finding consistently validated through both bioinformatics and RT-qPCR analyses." (PMID 41150779, 2025). "The RT-qPCR results were consistent with the bioinformatics analyses, confirming that BMP6 and SLC48A1 were differentially expressed between the endometriosis and control groups." (PMID 41150779, 2025). "BMP6 and SLC48A1 were significantly upregulated in endometriosis samples compared with controls in both the training and validation sets (p < 0.05)." (PMID 41150779, 2025). "In addition, this study found that SLC48A1 is upregulated in endometriosis and may drive disease progression by modulating iron metabolism." (PMID 41150779, 2025). "Furthermore, the Steiger test was TRUE for both genes, demonstrating the absence of reverse causality between BMP6, SLC48A1, and endometriosis." (PMID 41150779, 2025). "Therefore, SLC48A1 may act as a critical molecular link connecting lesion hemorrhage to disease progression via the heme iron recycling–iron overload–oxidative stress axis, representing a potential therapeutic target in endometriosis." (PMID 41150779, 2025). "BMP6 exhibited the strongest negative correlation with monocytes, whereas SLC48A1 demonstrated the strongest positive correlation with activated NK cells, suggesting their involvement in endometriosis through immune cell regulation." (PMID 41150779, 2025). "The exposure levels of BMP6 and SLC48A1 were shown to affect endometriosis, while endometriosis did not exert a reverse effect on the expression of BMP6 and SLC48A1." (PMID 41150779, 2025).
iron disorders (1 paper, 2020). "We propose that mutations in human SLC48A1 could contribute to idiopathic iron disorders." (PMID 34713217, 2020).
iron overload (1 paper, 2019). "We speculate that pharmacologic inhibition of SLC48A1 in humans would lead to tolerance and protection from heme toxicity and iron overload." (PMID 31571584, 2019).
malaria (1 paper, 2020). Malaria is a serious and sometimes fatal disease caused by a parasite that commonly infects a certain type of mosquito which feeds on humans. "Prior to our discovery of hemozoin in SLC48A1-deficient RES macrophages, hemozoin had only been observed in the lysosomal-like organelles of blood-feeding organisms that digest hemoglobin such as malaria parasites of the genus Plasmodium." (PMID 34713217, 2020).
sarcoma (1 paper, 2020). A usually aggressive malignant neoplasm of the soft tissue or bone. "Interestingly, NCOA4 and SLC48A1 are also included in the multigene signature for DFS, which implies that these two genes may play a more important role in the progression of sarcomas." (PMID 33489900, 2020).
cancer (3 papers, 2020 to 2023). A tumor composed of atypical neoplastic, often pleomorphic cells that invade other tissues. "Furthermore, overexpression of SLC48A1 promotes invasion, migration, and glycolysis, and cancer cell growth, which are associated with less favorable outcomes." (PMID 36844876, 2023). "Additionally, high expression of SLC48A1 drives glycolysis flux and promotes cancer cell growth, migration, and invasion, which is associated with poor prognosis." (PMID 35118074, 2021).
tumor (2 papers, 2020 to 2021). "At the same time, the correlation of the SLC48A1 and SLC39A8 genes with tumor-infiltrating immune cells was analyzed." (PMID 35118074, 2021).
SLC48A1 also shares sentences with these, for which no sentence is quoted: colorectal cancer (1 paper); infection (1); ovarian carcinoma (1).